PAX6 (paired box 6)
Diseases named in the same sentence as PAX6 in open-access papers (continued):
Sharing a sentence is not in itself a finding about the gene and the disease.
aniridia (continued). "The mutation affects a highly conserved amino acid located in the paired-domain of PAX6 - a hotspot for missense mutations that cause aniridia and other eye abnormalities." (PMID 36202929, 2023). "In search of literature, we also noticed the documentation of PAX6 c.220A>T (p.Ser74Cys) variant that has been linked with aniridia in the Clinvar database (Accession: VCA000578328.1)." (PMID 36843716, 2023). "The phenotypic spectrum of eye abnormalities of PAX6 mutations is highly variable and ranges from classical aniridia (usually due to loss-of-function mutations) to mild ocular phenotypes such as nystagmus and microphthalmia." (PMID 36202929, 2023). "In conclusion, our work supports the idea that cryptic splicing sites in intron 6 of PAX6 contribute to mis-splicing in congenital aniridia, expanding the knowledge on mutational mechanisms associated with PAX6." (PMID 36675087, 2023). "Aniridia is a highly penetrant autosomal dominant disease caused almost exclusively by haploinsufficiency of PAX6 (Paired box gene 6), a transcription factor essential for ocular development that regulates highly complex gene networks." (PMID 37269011, 2023). "The mutations in the PAX6 gene cause ocular abnormalities including aniridia in both vertebrate and invertebrate animal species." (PMID 36983625, 2023). "This 11p13 microdeletion contained essential conserved enhancer elements of PAX6, which was likely to be the cause of the familial aniridia in this family." (PMID 37752489, 2023). "Aniridia is a rare genetic condition that affects eye development and is most often caused by mutations that lead to the loss of one functional copy of the PAX6 gene." (PMID 37067366, 2023). "This study investigates the distribution of PAX6-associated congenital aniridia (AN) and WAGR syndrome across Russian Federation (RF) districts while characterizing PAX6 gene variants." (PMID 38002984, 2023). "Aniridia is an autosomal dominant disorder caused by haploinsufficiency of the highly conserved transcriptional factor PAX6 (Paired-box gene 6), which is involved in the morphogenesis and maintenance of ocular structures." (PMID 36675087, 2023). "This led Behaegel and colleagues to evaluate the outcomes of an allogeneic HLA-matched allo-CLET for the treatment of aniridia-associated keratopathy in 6 patients with aniridia, a rare genetic disorder due to mutations in the Pax6 gene." (PMID 36766837, 2023). "Mutations in the PAX6 gene cause anterior segment malformations including aniridia, accompanied by a range of ocular phenotypes such as keratitis, cataract, glaucoma, nystagmus, foveal hypoplasia, and optic nerve disorders." (PMID 36983625, 2023). "Genetic studies suggest that heterozygous mutations in the developmental regulator PAX6 gene or the related regulatory regions leading to haploinsufficiency are the main cause of congenital aniridia." (PMID 36983625, 2023). "PAX6 haploinsufficiency causes aniridia, a congenital eye disorder that involves the iris, and foveal hypoplasia." (PMID 36675087, 2023). "The majority of congenital aniridia and other ocular disorders such as Peters anomaly occur due to different mutations found in or around the transcription factor PAX6 gene (paired box 6, MIM 607108)." (PMID 36983625, 2023). "A study analysing mutations in PAX6 gene showed that MLPA enhanced the molecular diagnosis of aniridia." (PMID 35911417, 2022). "–48 Likewise, PAX6 is well known as a master regulator of eye formation in which mutations have largely been associated with aniridia, but mutations in this gene have also been identified in families with congenital cataracts." (PMID 35749127, 2022). "More than 90% of individuals with aniridia have heterozygous mutations detectable at the PAX6 locus that appear to result in loss-of-function." (PMID 36413568, 2022). "PAX6 was firstly proposed as the causative gene of congenital aniridia in 1991 by positional cloning." (PMID 36582291, 2022).
aniridia (continued). "PAX6 loss-of-function variants are the most common cause of aniridia, and variants throughout the gene have been linked to a range of ophthalmic abnormalities." (PMID 35034608, 2022). "Out of 70 individuals affected with aniridia, 24 different point mutations in the PAX6 gene were identified in 34 patients after sequencing." (PMID 35911417, 2022). "In summary, we identified the novel heterozygous c.114_119delinsAATTTCC: p.Pro39llefsTer17 variant of the PAX6 gene as a putative cause of aniridia in a Chinese family." (PMID 35034608, 2022). "We report spontaneous anterior lens capsule rupture as a novel phenotype of aniridia and three recurrent mutations and one novel mutation of PAX6 in families with aniridia." (PMID 36582291, 2022). "The ECS results showed that they were classified as ARC for GJB2, whereas the female partner had a P variant of autosomal dominant condition PAX6 related to aniridia." (PMID 36072675, 2022). "We identified that a novel PAX6 frameshift heterozygous deletion variant is the predominant cause of aniridia in this Chinese family." (PMID 35034608, 2022). "By analysing a Chinese family with a history of congenital aniridia, we identified a novel hybrid variant (c.114_119delinsAATTTCC: p.Pro39llefsTer17) in the PAX6 gene." (PMID 35034608, 2022). "Most aniridia cases are associated with mutations in the pair box 6 (PAX6) gene at chromosome 11p13." (PMID 36582291, 2022). "In the present study, we describe a novel PAX6 variant associated with congenital aniridia in a Chinese family." (PMID 35034608, 2022). "It has also been reported that missense mutations are usually associated with milder atypical aniridia phenotypes, probably resulting from the prediction that the PAX6 proteins of missense mutations retain some of their functions." (PMID 36582291, 2022). "In human, mutations in the PAX6 gene are linked to a variety of eye defects such as aniridia, corneal opacification or cataract, as well as autism spectrum disorder." (PMID 35281111, 2022). "The majority of PAX6 mutations result in null alleles and consequent PAX6 haploinsufficiency and lead to aniridia." (PMID 36582291, 2022). "It is still far from clear how PAX6 mutations translate into variable expressivity among individuals with aniridia from the same or different families." (PMID 36582291, 2022). "As supportive evidence, patients with PAX6 mutation who exhibit aniridia also have a smaller pineal gland, where melatonin is produced, and are often diagnosed with sleep disorders." (PMID 35682795, 2022). "Aniridia and associated ocular defects are triggered by a PAX6 haploinsufficiency that encodes a transcriptional regulator required for the eye development." (PMID 36011342, 2022). "The mutation or deletion of the SIMO element causes the defective maintenance of the expression of the PAX6 gene in the lens and therefore results in aniridia, even when the PAX6 gene is intact." (PMID 36011342, 2022). "Heterozygous PAX6 pathogenic variants or chromosome 11p13 rearrangements cause congenital aniridia, related phenotypes, and, on rare occasions, other phenotypes such as isolated optic nerve malformations, foveal hypoplasia, and achromatopsia." (PMID 35743132, 2022). "The phenotype of aniridia in patients with WAGR syndrome is caused by the haploinsufficiency of PAX6 (OMIM: 607108)." (PMID 36011342, 2022). "PAX6 haploinsufficiency tends to cause aniridia (OMIM 106210), a pan-ocular disorder characterised by partial or complete iris hypoplasia, foveal hypoplasia and nystagmus, with subsequent development of cataracts, glaucoma and corneal keratopathy." (PMID 33024313, 2021). "PAX6 is considered the master regulator of eye development, the majority of variants affecting this gene cause the pan-ocular developmental eye disorder aniridia." (PMID 33024313, 2021). "The novel 4.25 kb deletion in PAX6 gene of our study would further broaden the genetic defects of PAX6 associated with congenital aniridia." (PMID 34610801, 2021).
aniridia (continued). "Foveal hypoplasia can be found in patients with one of several other eye disorders such as albinism, PAX6 gene mutations with aniridia, isolated foveal hypoplasia, achromatopsia, retinopathy of prematurity, and Stickler syndrome." (PMID 33188472, 2021). "PAX6, which is associated with aniridia and associated ocular manifestations, including foveal hypoplasia and cataract, was excluded as the causative gene based on the absence of potentially disease-causing variants in this gene." (PMID 33418956, 2021). "The novel nonsense variation in PAX6 was the cause of aniridia in this family, which expanded the spectrum of the PAX6 mutation." (PMID 34016071, 2021). "Although no genotype-phenotype correlations are clearly established, missense variants affecting the DNA-binding paired domain of PAX6 are usually associated with non-aniridia phenotypes like microphthalmia, coloboma or isolated foveal hypoplasia." (PMID 33024313, 2021). "An iPSC line was derived from fibroblasts of a 34-year-old female with severe microphthalmia, aniridia, cataracts, optic nerve coloboma and nystagmus, and genetically diagnosed with a heterozygous missense mutation in PAX6 c.372C>A p.(Asn124Lys)." (PMID 33524672, 2021). "In conclusion, iPSCs were generated from a patient with a heterozygous c.372C>A p.(Asn124Lys) missense mutation in PAX6, associated with severe microphthalmia, aniridia and other ocular disorders." (PMID 33524672, 2021). "Similar situation has been observed for PAX6, a gene known to cause aniridia when mutated, in which several single nucleotide polymorphisms are significantly associated with myopia." (PMID 34926457, 2021). "Haploinsufficiency of PAX6 in mice causes the congenital condition aniridia, with defects in each of these organs and systems." (PMID 34065151, 2021). "Up to 90% of cases with aniridia can be explained by loss‐of‐function mutations in the PAX6 gene; rarely, disruption of FOXC1, PITX2, and other genes have been identified as causative." (PMID 33973683, 2021). "A lot of studies have reported that variants in the PAX6 gene can lead to the clinical symptom of aniridia." (PMID 34610801, 2021). "We present a longitudinal natural history study of patients with aniridia with molecularly confirmed PAX6 mutations over a mean 16.3-year follow-up." (PMID 34101622, 2021). "In the present study, we identified a novel heterozygous PAX6 nonsense mutation c.619A > T (p.K207*) in a Chinese autosomal dominant family with aniridia." (PMID 34016071, 2021). "Mutations leading to the C-terminal extension (CTE) of PAX6 protein are less common, with some reports linking these variants to more severe aniridia phenotypes, comparable to PTCs." (PMID 34101622, 2021). "Most forms of aniridia are caused by pathogenic variants affecting PAX6, a highly conserved “master regulator” of eye development, localized to 11p13, with a small fraction of cases remaining unexplained or due to pathogenic variants in ITPR1, FOXC1, or PITX2." (PMID 34573386, 2021). "The phenotype associated with the novel mutation was in line with classic aniridia related to PAX6 haploinsufficiency." (PMID 34016071, 2021). "When the classical aniridia phenotype is present, the diagnosis is straight forward and most commonly caused by heterozygous mutations on the PAX6 gene." (PMID 34065151, 2021). "PAX6 variant had been identified associated with aniridia and other ocular development abnormalities previously, while olfactory abnormalities and brain structure alterations in line with expression of Pax6 had also been documented recently." (PMID 34016071, 2021). "Aniridia phenotype associated with PAX6 haploinsufficiency almost present anterior segment and fundus abnormalities, while missense mutations in PAX6 were mostly associated with dysplasia of skeleton and central nervous system." (PMID 34016071, 2021).
aniridia (continued). "PAX6 variants have previously been shown to be implicated in aniridia, and as this variant co-segregated with the phenotype, it was considered as causative for disease in the patients." (PMID 34610801, 2021). "Homozygous mutations in the paired box protein, Pax6, which promotes development of the eye, nose, central nervous system, and the pancreas, are lethal while heterozygous mutations cause aniridia and other defects." (PMID 34366878, 2021). "A novel heterozygous PAX6 nonsense mutation c.619A > T (p.K207*) was identified in the Chinese autosomal dominant family with aniridia." (PMID 34016071, 2021). "Aniridia is most commonly caused by haploinsufficiency of the PAX6 gene, characterized by variable iris and foveal hypoplasia, nystagmus, cataracts, glaucoma, and aniridia-related keratopathy (ARK)." (PMID 34101622, 2021). "There were 62 families in total, including 60 patients from 36 families with familial aniridia, 18 patients with sporadic aniridia with de novo PAX6 pathogenic variants, and 8 individuals in which the family history was not documented." (PMID 34101622, 2021). "The spectrum of PAX6 mutations and clinical phenotypes of patients with aniridia have been well described, and most studies have reported no clear genotype-phenotype correlations." (PMID 34101622, 2021). "Aniridia is caused by heterozygous mutations involving the paired box 6 (PAX6) gene, which is considered the master regulator of the eye." (PMID 34101622, 2021). "The ataluren eye drops concentration at 1% was selected according to a preclinical study showing its efficacy in a Pax6-deficient mouse model of aniridia." (PMID 33375041, 2020). "While Pax6 gene mutations in humans are most commonly associated with aniridia, in mice and zebrafish, microphthalmia and severe anterior segment dysgenesis are observed." (PMID 33425902, 2020). "The most common form of aniridia occurring in around 90% of cases is caused by PAX6 haploinsufficiency due to intragenic mutation or chromosomal rearrangement in the PAX6 gene at 11p13." (PMID 33375041, 2020). "The most common form of aniridia occurring in around 90% of cases is caused by PAX6 haploinsufficiency." (PMID 33375041, 2020). "Correspondingly in humans, mutations in PAX6 can result in varied abnormalities of the eye such as Peter’s anomaly and aniridia, the metabolic disease diabetes or a combination of both, depending on the respective mutation." (PMID 33127955, 2020). "In conclusion, we identified a novel c.702_703delinsAT mutation of the PAX6 gene in a Chinese family with congenital aniridia." (PMID 32125788, 2020). "In this study, we report a Chinese family with congenital aniridia carrying a novel in‐frame nonsense mutation of the PAX6 gene." (PMID 32125788, 2020). "Congenital aniridia (AN) is caused by heterozygous mutations in the PAX6 gene (OMIM *607108; 11p13) or 11p13 deletions." (PMID 32948199, 2020). "According to a comprehensive review of PAX6 mutations, phenotypes have relied mostly on mutation spectrums and distributions; aniridia is typically caused by truncating mutations, while non-aniridia is generally caused by missense mutations." (PMID 32080308, 2020). "There are several research data confirming a direct correlation of PAX6 gene mutation with aniridia occurrence." (PMID 32545285, 2020). "Congenital PAX6-associated aniridia is a hereditary eye disorder caused by mutations or chromosome rearrangements involving the PAX6 gene." (PMID 32708836, 2020). "Embryos with putative null Pax6 mutations also show severe eye abnormalities and changes in brain development resembling human aniridia phenotypes." (PMID 32111086, 2020). "Mutations in human PAX6 gene are associated with various congenital eye malformations including aniridia, foveal hypoplasia, and congenital nystagmus." (PMID 32080308, 2020). "Congenital aniridia involves total or partial hypoplasia of the iris and is due to a deficiency in PAX6 gene expression." (PMID 32056389, 2020).
aniridia (continued). "Typically, PAX6 mutations are associated with aniridia, however, recent studies have reported cases with milder phenotypes with minimal to no iris abnormalities." (PMID 32744312, 2020). "WAGR syndrome (Wilms tumour, aniridia, genitourinary anomalies and mental retardation/intellectual disability), is caused by contiguous deletion of PAX6 and WT1 on chromosome 11p." (PMID 30242502, 2019). "In the PAX6 Mutations Database, approximately 15% of all variants are located in the intronic regions and they are generally associated with classical aniridia phenotypes." (PMID 31861090, 2019). "Approximately 80% congenital aniridia cases are caused by the gene mutation of human paired box-6 (PAX6)." (PMID 30621664, 2019). "Patients with PAX6-associated microphthalmia often have a complex phenotype, with associated ocular abnormalities including aniridia, iris hypoplasia, coloboma and optic nerve hypoplasia." (PMID 31416264, 2019). "Most PAX6 mutations causing aniridia are heterozygous, sporadic, or familial in an autosomal dominant manner, with significant phenotypic variability." (PMID 31861090, 2019). "A novel deletion in the PAX6 gene was identified in a Chinese family associated with aniridia, which expands the spectrum of the PAX6 mutation and its associated phenotype." (PMID 30621664, 2019). "In contrast to PAX6-associated aniridia, the ocular defects in GS are essentially restricted to the iris and the variable presence of iridolenticular strands." (PMID 30242502, 2019). "Permanent reduction in PAX6 expression levels is known to cause aniridia in eyes of PAX6+/− patients." (PMID 31405104, 2019). "Aniridia is a congenital ocular abnormality, in which the most characteristic feature is iris hypoplasia associated with the gene mutation of paired box-6 (PAX6) in most cases." (PMID 30621664, 2019). "In conclusion, the phenotype of aniridia patients in a four-generation family was analyzed, and a novel deletion in PAX6 (c.435_445delTAGCGAAAAGC) was identified as the cause of aniridia in this family." (PMID 30621664, 2019). "Expression of Pax6 is dosage dependent as mutation or missing allele leads to aniridia in humans (Review in16) and the small eye (sey, Pax6+/−) in mouse animal model." (PMID 31278274, 2019). "Up to one-third of sporadic cases of aniridia are associated with PAX6 and WT1 deletions, while the remaining two-thirds are considered to be most likely caused by de novo point mutations." (PMID 31861090, 2019). "Classical aniridia is strongly associated with heterozygous loss-of-function of PAX6 (Paired box 6, OMIM 607108, hg38 chr11:31784792–31811353)." (PMID 30242502, 2019). "Recently, missense mutations in TRIM44 gene, located 4 Mb away from PAX6, were identified in a Chinese family with aniridia, cataracts and glaucoma." (PMID 31861090, 2019). "The majority of PAX6 mutations result in null alleles and consequent PAX6 haploinsufficiency and they are known to cause aniridia." (PMID 31861090, 2019). "Aniridia is predominantly associated with truncating mutations in the PAX6 gene, while missense mutations usually lead to non-aniridia phenotypes." (PMID 29460221, 2018). "In many studies it was proven that aniridia is a typical autosomal dominant disorder resulting from inactivation of one allele of the PAX6 gene, predominantly through intragenic mutations leading to premature termination of the protein." (PMID 29460221, 2018). "This is the first report confirming parental PAX6 mosaicism as a cause of disease recurrence in aniridia and other related phenotypes." (PMID 30386378, 2018). "Aniridia, a congenital ocular disorder caused by heterozygous loss-of-function mutations in PAX6, needs new vision saving therapies." (PMID 30258099, 2018). "We investigated the presence of parental mosaicism associated with disease-causing PAX6 variants in 3 families from a large cohort of Spanish patients with aniridia (n = 78) and other ODAs (n = 169)." (PMID 30386378, 2018).